ALB (albumin)
Diseases named in the same sentence as ALB in open-access papers (continued):
Sharing a sentence is not in itself a finding about the gene and the disease.
coronary artery disease (continued). "While the distribution of coronary artery disease and ischemic cardiomyopathy was similar across albumin quartiles, patients in Q1 underwent coronary angiography less often than those with higher albumin levels." (PMID 41452958, 2026). "Despite advances in treatment and the potential role of serum albumin as a prognostic biomarker, the mortality rate of individuals with coronary heart disease (CHD) continues to increase." (PMID 40927110, 2025). "Recent studies have shown that alkaline phosphatase to albumin ratio (APAR) is a prognostic biomarker for coronary heart disease and cancer." (PMID 40371078, 2025). "In cases of ACS and stable coronary artery disease (including previous myocardial infarction and heart failure), low levels of albumin are of prognostic value." (PMID 40124630, 2025). "All analyses were adjusted for age, albumin, malignancy, total protein, coronary artery disease, blood urea nitrogen, creatinine, history of AKI, and hs-CRP." (PMID 40305332, 2025). "Evaluation of the predictive ability of C-reactive protein-to-albumin ratio value for coronary artery disease severity using a simple linear regression model." (PMID 40922854, 2025). "In patients with stable coronary artery disease, decreased albumin levels were also independently related to worse cardiovascular outcomes." (PMID 41245592, 2025). "Univariate logistic regression analysis revealed that AF was associated with a history of ischemic heart disease, having an AVF created before the initiation of hemodialysis, and albumin levels at the start of hemodialysis." (PMID 40131887, 2025). "Uric acid to albumin ratio (UAR) has emerged as a marker for predicting events related to coronary artery disease (CAD)." (PMID 41305749, 2025). "In the PRACTICEstudy, a 60-month follow-up of 14,994 coronary artery disease patients revealed aU-shaped relationship between serum albumin and the risks of major adversecardiovascular events." (PMID 40927110, 2025). "The results of this study show that in type 2 diabetic patients with stable coronary artery disease, elevated UAR was closely associated with reduced collateral formation, which was superior to serum uric acid and albumin alone." (PMID 41497488, 2025). "In our study, we addressed potential confounding by adjusting all analyses for multiple factors, including age, albumin, malignancy, total protein, coronary artery disease, blood urea nitrogen, creatinine, history of AKI, and hs-CRP." (PMID 40305332, 2025). "Machine learning models consistently identified coronary artery disease (CAD), hypertension, renal insufficiency, and albumin (Alb) levels as significant HF risk factors." (PMID 40969263, 2025). "The uric acid/albumin ratio (UAR) has been shown to correlate with coronary disease severity and clinical outcome." (PMID 41497488, 2025). "Ischemia-modified albumin is a new marker used in the diagnosis of coronary artery disease in recent years." (PMID 39336570, 2024). "It revealed that a low serum albumin level independently predicted the occurrence of ischemic heart disease, myocardial infarction, and ischemic stroke." (PMID 38580915, 2024). "The uric acid-to-albumin ratio (UAR) has been found to be related to the prognosis of coronary heart disease." (PMID 38443781, 2024). "Alongside serum 1,25(OH)2D levels, significant factors tied to LVH encompassed age, coronary heart disease, blood pressure, hemoglobin, urinary albumin levels, phosphate, eGFR, CRP, and intact PTH." (PMID 38722953, 2024). "Molecular docking results showed that the active components of YMOS and key proteins, namely ALB and apigenin, caffeic acid, daidzein, ferulic acid, kaempferol have stable interactions in the context of coronary heart disease complicated with anxiety." (PMID 39470548, 2024). "The SHAP method revealed that AKI stage, albumin, lactate dehydrogenase, aspirin and coronary heart disease were the top 5 predictors of AKD." (PMID 39211338, 2024).
coronary artery disease (continued). "The alkaline phosphatase-to-albumin ratio (APAR) is correlated to worse prognosis in coronary artery disease, cancer, and acute renal failure." (PMID 38326383, 2024). "Low levels of albumin have been shown to have prognostic value in both coronary artery disease and stable coronary artery disease." (PMID 38326538, 2024). "Multivariate analysis revealed that the factors independently associated with mortality in all cases were age 80 or over, which are dyslipidemia, coronary artery disease, hemodialysis, and low serum albumin." (PMID 38919317, 2024). "The protective effect of serum albumin is diminished in hypertensive and diabetic patients, further contributing to the development of diseases such as ischemic stroke, heart failure, and coronary artery disease." (PMID 37693342, 2023). "Risk factors associated with PD included: ASA classification, age, albumin level, hemoglobin level, preoperative PSQI score, operation type, coronary heart disease and postoperative ICU admissions (p < 0.05)." (PMID 37978346, 2023). "Female gender, atrial fibrillation, coronary heart disease or heart failure, recanalized treatment, older patients, lower hemoglobin, albumin, eGFR, and white blood cell counts, and higher NIHSS scores are all related to poor outcomes." (PMID 37606393, 2023). "As an extension of its predictive value, the ratio of CRP to albumin can be used to predict coronary artery disease and IVIG resistance in children with KD35." (PMID 36854770, 2023). "The significantly prognostic value of fibrinogen-to-albumin ratio (FAR) has been proved in patients with coronary artery disease and different oncologic disorders." (PMID 36755341, 2023). "It has been shown that a lower albumin level is related to coronary artery disease severity and poor outcomes in CAD." (PMID 38022331, 2023). "Albumin is an important protein for atherosclerosis and coronary artery disease due to its anti-inflammatory effect, as well as its inhibiting platelet aggregation and anticoagulant effects." (PMID 37109621, 2023). "Variables associated with 5-year renal disease progression in the univariate logistic analysis were coronary artery disease, heart failure, atrial fibrillation, 24 h-urinary albumin, 24 h-urinary protein, and intrarenal RI." (PMID 35683384, 2022). "The lower PA group was older, had a higher proportion of women, a lower body mass index, lower albumin, cholesterol, uric acid, and phosphorus levels, and a higher incidence of history of coronary artery disease than the higher PA group." (PMID 35758371, 2022). "Another early study found that replacing total cholesterol to HDL with total cholesterol to albumin in general outpatients was likely to weaken the relation with coronary heart disease." (PMID 35755025, 2022). "Most of the covariates of the matched cohorts were similar between the two groups, except for weight, body mass index (BMI), serum albumin, hemoglobin, and two comorbid conditions (coronary heart disease and AIDS/HIV)." (PMID 36432473, 2022). "Inflammation plays a crucial role in coronary atherosclerosis progression, and growing evidence has demonstrated that the fibrinogen-to-albumin ratio (FAR), as a novel inflammation biomarker, is associated with the severity of coronary artery disease (CAD)." (PMID 35313877, 2022). "Serum albumin levels had been affirmed to be inversely related to occurrence of ischemic heart disease." (PMID 35300600, 2022). "Univariate Cox regression analysis indicated that age, SBP, DBP, FPG, albumin, haemoglobin, BMI, cerebral infarction, coronary heart disease, nutritional status and decreased CC were significantly correlated with mortality." (PMID 35193560, 2022). "We find that there is lower plasma albumin and hemoglobulin in elderly coronary artery disease patients who had worsening renal function or cardiac function." (PMID 34606471, 2021).
coronary artery disease (continued). "In a cohort study of 759 patients with AIS followed for 3 months, a poor outcome was independently related to low serum albumin level, ischemic heart disease, and infarction size." (PMID 35095715, 2021). "Patients with cerebrovascular disease or coronary artery disease had higher levels of ionised calcium (Ca2+) along with reduced total protein and albumin, collectively suggestive of exhausted serum Ca2+-binding capacity." (PMID 34830334, 2021). "Frail patients—e.g., those requiring assistance to transfer, or those with ischemic heart disease or serum albumin < 3.5 g/dL—experienced higher odds of infection." (PMID 33857168, 2021). "Hyperlipidemia, ischemic heart disease, corticosteroid administration, perioperative blood transfusion, and albumin level at POD 3 were found to be significant factors associated with postoperative VTE in univariate analysis." (PMID 36776649, 2021). "Participants with incident PH were more likely to have atrial fibrillation, coronary artery disease, peripheral artery disease, cerebrovascular disease, a history of heart failure and a higher urinary albumin:creatinine ratio." (PMID 34640520, 2021). "There was lower plasma albumin (35±4 and 37±4g/l, p=0.011), lower hemoglobulin (112±26 and 121±21, p=0.038) in coronary artery disease patients who died compared with the living." (PMID 34606471, 2021). "The serum of patients with coronary artery disease or cerebrovascular disease displayed an increased propensity to form CPPs in combination with elevated ionised calcium as well as reduced albumin levels, altogether indicative of reduced Ca2+-binding capacity." (PMID 34830334, 2021). "Of ACS patients, low serum albumin level at admission was also an independent predictor of heart failure, extent and complexity of coronary artery disease, and contrast-induced acute kidney injury." (PMID 31815281, 2020). "Low albumin levels are known to have prognostic significance in cases such as acute coronary syndrome, heart failure, and stable coronary heart disease." (PMID 33094574, 2020). "As a result, low levels of albumin in serum are related to different types of cardiovascular disease, such as coronary artery disease, heart failure, atrial fibrillation and strokes." (PMID 33322022, 2020). "A Chinese study of 410 patients with recovery revealed that coronary heart disease, albumin levels, and the initial time of antiviral treatment were independent factors associated with SARS-CoV-2 viral shedding." (PMID 33260421, 2020). "In males, ischemic heart disease (IHD), and low serum albumin (S-Alb) were associated with all-cause mortality." (PMID 31945095, 2020). "Low serum albumin concentration was proved to be related to the development of ischemic heart disease and was proved to be an independent predictor of first or recurrent myocardial infarction (MI)." (PMID 32934964, 2020). "Previous studies showed that fibrinogen-to-albumin ratio (FAR) regarded as a novel inflammatory and thrombotic biomarker was the risk factor for coronary artery disease (CAD)." (PMID 32879878, 2020). "Serum CRP-to-albumin ratio has been shown previously to be a predictor for overall survival in several cancer states and in coronary artery disease." (PMID 31828049, 2019). "After multivariable analysis, increased age and E/LA strain, the presence of coronary artery disease, and decreased albumin were still the major predictors of increased total mortality." (PMID 31905735, 2019). "In patients with coronary artery disease, lower circulating ucMGP levels were correlated with a decrease in eGFR, but albumin-to-creatinine ratio remained unaffected." (PMID 30934817, 2019). "This was reduced slightly to 36% (HR: 1.36; 95% CI 1.15–1.62) when we adjusted for age, gender, duration of insulin use, albumin, glomerular filtration rate, lipid profile, and coronary heart disease history." (PMID 28830436, 2017).
coronary artery disease (continued). "Hypomethylation of P2RY12 promoter was associated with clopidogrel resistance in coronary artery disease (CAD) patients with smoking, albumin <35 g/L, and alcohol abuse." (PMID 28335443, 2017). "Multivariate analysis revealed that age, history of coronary artery disease, serum albumin level, and AKI were independent predictors of long-term mortality." (PMID 28426743, 2017). "A higher HOMA-IR value, BMI level, glucose, total bilirubin, albumin, and UA, and a higher prevalence of coronary heart disease and heart attack were observed in the highest MAMC quartile compared to the lowest quartile." (PMID 29108358, 2017). "Results from this study are applicable to coronary artery disease patients with albumin ≤35 g/L, current smoking or alcohol abuse." (PMID 27686864, 2016). "Our observation that the albumin levels are significantly low is supported by a meta-analysis of eight prospective population based studies of albumin and coronary heart disease before 199841." (PMID 27350024, 2016). "Participants with previous ischemic heart disease, higher systolic blood pressure, and elevated levels of creatinine, serum albumin, or glycosylated hemoglobin tended to be more likely to have CMBs (p<0.1)." (PMID 26421848, 2015). "In summary, the excessive drinking, coronary heart disease, preoperative albumin, intraoperative blood transfusion (>600 mL), soft remnant pancreas, and laparoscopic operation were risk factors affecting PF incidence after PD." (PMID 25788941, 2015). "Univariate logistic regression analysis showed that there were significant associations between PF occurrence rates and patient-related factors of excessive drinking (P = 0.029), coronary heart disease (P = 0.029), and preoperative albumin (P = 0.006)." (PMID 25788941, 2015). "A decrease in albumin is related to coronary heart disease and heart failure, and is in agreement with our observation of decreased serum albumin under cardiotoxic conditions." (PMID 23940596, 2013). "Autoantibodies to N-homocysteinylated albumin have been reported as a marker for coronary artery disease." (PMID 17125526, 2006). "The authors suggest that this relationship may stem from fibrinolysis driven by low albumin levels and elevated fibrinogen as indicators of chronic inflammation in coronary artery disease." (PMID 40095623, 2025). "Additionally, coronary heart disease (P = 0.004), sedentary time (P = 0.015), and urinary albumin/creatinine ratio (P = 0.002) also showed significant differences among the groups." (PMID 39717100, 2024). "Patients in facilities with higher peritonitis rates tended to be older with shorter PD vintage, have greater use of CAPD, have coronary artery disease or other cardiovascular diseases and have slightly worse nutritional indicators [e.g. lower body mass index (BMI), serum albumin and phosphorus]." (PMID 39050865, 2024). "The proportion of male patients was higher (75% vs. 54.4%, p = .018), the percentage of ischemic heart disease was higher (31.8% vs. 16.7%, p = .036), ALB level was lower (36.8 ± 3.3 vs. 38.8 ± 3.2, p = .001), serum phosphorus was lower (1.59 ± 0.39 vs. 1.77 ± 0.44, p = .019)." (PMID 38549547, 2024). "Unlike other nutritional scores, the CONUT score relies mainly on objective values of serum albumin (ALB), total lymphocyte count (TL), and total cholesterol (TC), and is primarily used to evaluate the prognosis of cancer, coronary artery disease, and patients undergoing dialysis." (PMID 39036498, 2024). "Similarly, albumin, as an inflammation biomarker, has been reported to be related to the prognosis of coronary artery disease and AMI." (PMID 36737704, 2023). "A history of coronary artery disease, multiple inotrope use, ejection fraction <40%, lower hemoglobin concentration, longer cardiopulmonary resuscitation duration, albumin infusion, and renal replacement therapy were identified as independent prognostic factors for in-hospital mortality." (PMID 35321103, 2022).
coronary artery disease (continued). "Increased AoAC, older age, female sex, coronary artery disease, and decreased albumin were associated with an increase in CTR, and older age, cerebrovascular disease, decreased albumin, increased Kt/V, and the use of antiplatelet agents were associated with an increase in AoAC." (PMID 34442433, 2021). "A previous study showed an inverse relationship between platelet activation and serum albumin <3.5 g/dL in patients affected by stable coronary artery disease but data regarding COX-1 inhibition as well as its impact with clinical outcomes was not investigated." (PMID 34239442, 2021). "Decreased albumin levels have also been found in some cardiovascular diseases, of which inflammatory reaction participates in the pathogenesis, including heart failure and coronary heart disease." (PMID 32778051, 2020). "Retinopathy treated with laser (32 vs 11%, p = 0.003), urinary albumin/creatinine ratio >3 mg/mmol (61 vs 31%, p = 0.001), coronary arterial disease (90 vs 73%, p = 0.04) and insulin treatment (77 vs 42%, p = 0.0003) were significantly more common in patients with neuropathy." (PMID 32092076, 2020). "Given its anti-inflammatory, antioxidant, anticoagulant, and anti-platelet aggregation activity, serum albumin may contribute to the progression of coronary artery disease." (PMID 31815281, 2020). "However, serum albumin cut-off points for predicting retinopathy and coronary artery disease complications were significant (respectively)." (PMID 31777503, 2019). "In a univariate logistic analysis, the significant predictors of 6-month mortality were female gender, age > 75 years, ischemic heart disease, congestive heart failure, dysrhythmia, low albumin levels, unplanned dialysis, functional dependence, cognitive impairment, and being institutionalized." (PMID 29317867, 2017). "Our results showed that the excessive drinking, coronary heart disease, preoperative albumin, intraoperative blood transfusion, texture of the remnant pancreas, methods of anastomosis, laparoscopic operation, and professional group were independently associated with PF occurrence." (PMID 25788941, 2015). "The American Society of Anesthesiologists (ASA) classification, age, type of muscle relaxant, smoking, low albumin levels, duration of surgery, type of anesthesia, and other comorbidities (like COPD, coronary artery disease, and kidney failure) are associated with the development of complications." (PMID 24906620, 2014). "Additionally, in a cohort of 1567 patients diagnosed with coronary artery disease, a prolonged QTc interval correlated with significantly lower serum albumin levels, a higher total white blood cell count, and higher levels of hs‐CRP, indicating a potential link with inflammatory processes." (PMID 40898929, 2026). "Coronary artery disease (CAD) is a major global health issue, and its severity assessment via the C-reactive protein-to-albumin ratio (CAR) is cost-effective and simple." (PMID 40922854, 2025). "Several studies have suggested that the measurement of structurally modified albumin could assist with monitoring oxidative stress in several clinical conditions, such as renal failure, ischemic heart disease, acute appendicitis, cerebral infarction, and pre-eclampsia." (PMID 38539812, 2024). "The fibrinogen-albumin-ratio (FAR), a novel biomarker of inflammation, is associated with the severity of coronary artery disease (CAD)." (PMID 37016312, 2023). "GNRI, as an index combining BMI and albumin, has recently seen wide use as an index for evaluating nutritional status, and has also been reported as a useful parameter for determining prognosis in patients with haemodialysis, chronic heart failure, coronary artery disease and critical limb ischemia." (PMID 34996387, 2022).